IL10 (interleukin 10)
Diseases named in the same sentence as IL10 in open-access papers (continued):
Sharing a sentence is not in itself a finding about the gene and the disease.
breast cancer (continued). "IL-10 downregulates the expression of Th1-type cytokines and increases the immune tolerance of cancer in the tumor microenvironment, while IL-1β is associated with an increased risk for bone metastasis in human breast cancer." (PMID 38397942, 2024). "Furthermore, the suppressive role of MEIS2 in breast cancer cell proliferation is associated with the IL10 expression and myeloid cells infiltration." (PMID 38711262, 2024). "Furthermore, our studies suggest that MEIS2 downregulates the expression of IL10 to suppress breast cancer growth, and MEIS2‐IL10 signaling is partially associated with MDSCs infiltration in BC." (PMID 38711262, 2024). "The underlying mechanism may be that MEIS2 affected breast cancer cell proliferation, migration, as well as the infiltration of myeloid cells in BC by regulating the IL10 expression." (PMID 38711262, 2024). "Moreover, increased IL-10 secretion is associated with aggressive breast cancer via the transformation of M1 macrophage to an M2 angiogenic phenotype." (PMID 37238871, 2023). "Conversely, IL-10 is a risk factor for HER2-negative breast cancer." (PMID 37910571, 2023). "In summary, our results demonstrate that TNBC cells but not HR+ cells induce a distinct population of M2-like TAMs that express M1-associated genes and secrete a considerable amount of IL-10 and IL-6, which in turn promotes breast cancer cell proliferation and metastasis." (PMID 35960749, 2022). "Importantly, we found that the immunosuppressive cytokine, IL-10 was positively associated with DVL-1 mRNA expression in breast cancer patients." (PMID 34659647, 2021). "IL-10 haplotype frequencies and the association with breast cancer risk." (PMID 32380517, 2020). "Our findings suggest that variants of IL-10 may be likelihood risk factors for the development and progression of breast cancer." (PMID 32380517, 2020). "To verify whether MTDH and IL-10 protein expressions were linked with clinicopathological parameters of breast cancer, we enrolled 265 breast cancer patients and performed immunohistochemistry of MTDH and IL-10." (PMID 33003428, 2020). "This study analyzes single nucleotide polymorphisms in interleukin 10 and tumor necrosis factor α genes and their contribution to breast cancer phenotype, lymph node status and survival in a group of young Lithuanian women with early-stage breast cancer patients." (PMID 26112140, 2015). "NFKB1 c.-798_-795delATTG ins/del and del/del genotypes, and IL-10 c.-854 TT genotype were associated with increased breast cancer risk, while IL8 c.-352 TT genotype, TNF c.-418 GA and AA genotypes, and c.-488 GA genotype were significantly associated with a reduced risk." (PMID 25559835, 2014). "However, 5 out of 8 combinations showed significant association with breast cancer risk and only three combinations of IL-8 and IL-10 polymorphisms showed significant association with breast cancer risk." (PMID 25559835, 2014). "In agreement with this hypothesis, it was shown that topical imiquimod therapy in a murine breast cancer model was associated with high IL-10 levels and IL-10 blockade markedly improved antitumor activity of imiquimod." (PMID 22927956, 2012). "We genotyped 315 patients with breast cancer and 322 healthy control subjects for -1082A/G, -819T/C and -592A/C single nucleotide polymorphisms in the promoter region of the IL-10 gene by polymerase chain reactionerestriction fragment length polymorphism (PCR-RFLP)." (PMID 20553628, 2010). "Recent data suggest that polymorphic variations in the promoter sequences of IL-10 gene may influence the gene expression and consequently play a certain role in susceptibility and clinical course of breast cancer." (PMID 20553628, 2010). "Moreover, another study from the Italian population showed that the IL-10 -1082AA genotype was correlated with a marked increase in breast cancer risk." (PMID 20553628, 2010).
breast cancer (continued). "The goal of this study was to evaluate whether IL-10 gene promoter -1082A/G, -819T/C and -592A/C polymorphisms and haplotypes were associated with breast cancer in a Han Chinese population." (PMID 20553628, 2010). "This study was performed to determined whether polymorphisms in the IL-10 gene promoter were associated with breast cancer in a Chinese Han population." (PMID 20553628, 2010). "This supports the observation that SNPs of XPD (ERCC2), BARD1 and IL-10 may be good candidates for breast cancer predisposition, which may also modify the effect of BRCA1 in carriers." (PMID 16672066, 2006). "The aim of this study was to evaluate polymorphisms in specific cytokine genes [IL1A +4845G>T, IL1B -511C>T, IL1B +3954C>T, IL1RN +2018T>C, IL4R -1902A>G, IL6-174G>C and IL10-1082G>A] in a case control model to determine any associations with breast cancer susceptibility, severity and survival." (PMID 16842617, 2006). "In breast cancer, its prognostic impact appears to depend on context: some studies of early-stage breast cancer paradoxically noted that IL-10 was associated with better prognosis in certain hormone receptor-positive cases, possibly due to IL-10 reducing harmful inflammation." (PMID 41007766, 2025). "In murine models, the 4T1 breast cancer line triggers the proliferation of tumor-associated Bregs, which suppress immune responses by secreting anti-inflammatory mediators such as interleukin 10 (IL-10), interleukin 35 (IL-35), and transforming growth factor beta (TGF-β)." (PMID 39507526, 2024). "Therefore, it is reasonable to assume that the NDRG2-induced reduction in IL-10 signaling may be associated with PD-L1 downregulation in breast cancer cells." (PMID 34885221, 2021). "Hypothesizing that gene amplification leads to an increase in protein expression, IL10 immunosuppressive properties could the metastatic potential of breast cancer, increasing the risk of lymph node involvement, which represents a well-known predisposing factor for BCLR." (PMID 32300557, 2020). "Thus, IL-10 has been suggested as a potential prognostic marker for breast cancer, and there may be a genetic correlation between IL-10 and breast cancer susceptibility." (PMID 32380517, 2020). "However, whether IL-10 upregulated ILT-4 expression through enhancing its promoter activity, and what underlying mechanism of ILT4 and IL-10 act in breast cancer warrant further exploration." (PMID 24762057, 2014). "Findings of our study are further supported by a recent study showing that the low-expression allele and haplotype were associated with reduced disease-free survival and the IL-10 gene polymorphisms may be a potential prognosis marker in breast cancer for disease-free survival." (PMID 20553628, 2010). "The results from our study do not support the hypothesis that the cytokine polymorphisms studied [IL1A +4845G>T, IL1B -511C>T, IL1B +3954C>T, IL1RN +2018T>C, IL4R -1902A>G, IL6-174G>C and IL10-1082G>A] are associated with breast cancer susceptibility and severity." (PMID 16842617, 2006). "The anti-inflammatory cytokine IL-10, expressed by immune cells, including MCs, is also suppressed by breast cancer cells." (PMID 41596472, 2026). "Beyond myeloid cells, regulatory B cells that express high levels of PD-L1 inhibit T-cell anti-tumor response via interleukin-10 (IL-10) signal in breast cancer." (PMID 41486149, 2026). "While plasma ACE2 was significantly elevated in breast cancer patients (p = 0.0005), IL-10 was significantly suppressed (p = 0.0420)." (PMID 42193411, 2026). "TAM suppresses CD103+ DC IL-12 production and T cell activation in breast cancer by secreting IL-10." (PMID 40422244, 2025). "And B cells were found to evidently increase their expression of IL‐10, PD‐L1 in sGRP78hi breast cancer samples from patients and mouse models." (PMID 40936109, 2025).
breast cancer (continued). "Conversely, in metastatic breast cancer cells, IL-10 expression can downregulate cell-mediated immune responses, limit antigen presentation, and enhance immunosuppressive signaling, facilitating tumor progression." (PMID 41155372, 2025). "The IL-10/STAT3/Bcl-2 axis plays a pivotal role in mediating TAM-induced breast cancer cell survival and paclitaxel resistance." (PMID 40909271, 2025). "There is currently inadequate evidence to suggest IL-10 as a possible preventative mediator in obese breast cancer patients against an enzyme (aromatase)." (PMID 40584290, 2025). "Llanes-Fernándeza et al122 previously reported that 85% (23 out of 27) of the breast cancer tissue studied from elderly individuals showed significant IL-10 expression (STAT3 in cancer cells)." (PMID 40584290, 2025). "The concentrations of anti-inflammatory cytokines IL-4 and IL-10 increased maximally in the subgroups of HER2-positive breast cancer: luminal B(+) (+108.1%, p = 0.0006 and +163.6%, p = 0.0000) and non-luminal (+105.6%, p = 0.0015 and +142.7%, p = 0.0000)." (PMID 40429927, 2025). "In the context of breast cancer, IL-10 is predominantly produced by immune cells within the tumor microenvironment, particularly by M2-polarized macrophages and by certain regulatory T cells." (PMID 41007766, 2025). "OP bone cultivated with breast cancer cells had higher IL-10 levels than healthy bone, indicating OP inhibits immune response." (PMID 40584290, 2025). "Surprisingly, IL-10 has demonstrated beneficial effects in both in vivo and in vitro obese postmenopausal breast cancer models." (PMID 40584290, 2025). "Further studies are clearly required to elucidate the mechanisms leading to elevated IL‐10 levels in the brain of mice that have been inoculated with mammary tumour cells but have overcome that significant immune challenge." (PMID 40172096, 2025). "Further studies are needed to clarify the role of these cytokines in breast cancer patients undergoing chemotherapy, particularly in the case of IL-10." (PMID 41155372, 2025). "XIST-deficient breast cancer EVs suppress TIMP-2 via exosomal miR-503, polarizing microglia toward an M2 phenotype that secretes immunosuppressive factors (IL-10, TGF-β) to inhibit T-cell proliferation." (PMID 40564894, 2025). "Promoting tumor growth, migration, and M2 macrophage polarization, IL-19 has been shown to contribute to an immunosuppressive microenvironment in breast cancer and is a member of the IL-10 cytokine family." (PMID 41348904, 2025). "A recent study found that serum levels of cytokines, such as TNF-α, IL-6, IL-8, and IL-10, differ significantly between patients with breast cancer menopause and controls." (PMID 40584290, 2025). "There is evidence that IL‐10 secreted by M2 TAMs facilitate colorectal cancer and breast cancer progression." (PMID 38506082, 2024). "In line with our results, high tissue expression of IL-10 was associated with improved DFS and BCSS in a series of 1380 early breast cancer patients in univariate analysis." (PMID 38594742, 2024). "Proinflammatory cytokines IL-6 and IL-8 and anti-inflammatory cytokine IL-10 play vital roles in breast cancer progression." (PMID 38314029, 2024). "In 2019, a study examining breast cancer patients revealed that the presence of IL-10+ Bregs was augmented in parallel with Tregs within primary tumors, correlating with shorter relapse-free intervals." (PMID 39507526, 2024). "Results show that the knockdown of MEIS2 in breast cancer cells up‐regulates the IL10 expression, but MEIS2 overexpression opposed the effect on IL10 expression." (PMID 38711262, 2024). "The role of IL-10 is anti-inflammatory; however, several studies have reported a role for IL-10 in breast cancer, as IL-10 mRNA was found to be highly expressed in breast cancer cells." (PMID 38785550, 2024).
breast cancer (continued). "Using tensor factorization to model this multidimensional data, we found that breast cancer patients exhibited widespread alterations in response, including drastically reduced response to IL-10 and heightened basal levels of pSmad2/3 and pSTAT4." (PMID 39389979, 2024). "Other studies have shown that IDO in breast cancer mediates MDSC-induced T cell proliferation and Th1 polarization inhibition, promotes T cell apoptosis and the secretion of immunosuppressive cytokines (IL-10 and TGF-β), causing breast cancer immune escape." (PMID 39192979, 2024). "In CLL and breast cancer patients, reduced IL-10 expression or impaired IL-10R-STAT3 signaling is correlated with increased frequencies of exhausted CD8+ T cells." (PMID 39281678, 2024). "MEIS2 mediates breast cancer cell growth and the infiltration of myeloid cells by regulating IL10 expression." (PMID 38711262, 2024). "CD19+B cells are thought to promote breast cancer development and metastasis through the secretion of IL-10 and induction of the conversion of CD4+T cells to Treg in the mouse models." (PMID 38263363, 2024). "Our study demonstrates that the tumor suppressor of MEIS2 in breast cancer progression is partially via down regulating the expression of IL10 and promoting myeloid cells infiltration." (PMID 38711262, 2024). "CXCL18 promotes tumor growth and invasion in breast cancer by inducing IL-4, IL-13, and IL-10 in TAMs." (PMID 39309874, 2024). "A study with a mouse 4T1 model of breast cancer demonstrated that the secretion of IL-10 by B lymphocytes acts in a TGF-β-dependent manner to promote the conversion of naive CD4+ T cells to Foxp3+ Tregs." (PMID 38533507, 2024). "Efferocytosis of the breast cancer cell line MCF-7 by the mouse macrophage cell line Raw267.4 increases the expression of M2-associated cytokines IL-4 and IL-10, and expression of Tgfb1 mRNA." (PMID 37644281, 2023). "In prostate or breast cancer, IL-10+CD19+ cells suppress effector immune cells in the tumor microenvironment by producing IL-10, and promote cancer metastasis by inducing regulatory T cells (Tregs) and releasing anti-inflammatory mediators." (PMID 37946227, 2023). "The serum IL-10 levels are higher in the breast cancer patients than that in healthy females, and further increased with cancer progression." (PMID 36693957, 2023). "In THP-1 macrophages, efferocytosis of breast cancer cell lines MDA-MB-231 and 4T1 increases IL-10 and decreases IL-6 secretion, an M1-associated cytokine." (PMID 37644281, 2023). "This information emphasizes the possible immunosuppressive and anti-inflammatory effects of IL-10, such as the modeling of apoptosis and reduction of angiogenesis in cases of regression and as a beneficial prognostic factor in canine mammary cancer." (PMID 37410738, 2023). "Some cytokines (leptin, IL-1β, IL-6, IL-8, IL-23, IL-17, TGF-β, IL-10) are mostly reported to stimulate while others (Il-2, IL-12, IFNs) inhibit breast cancer proliferation and/or invasion." (PMID 36835413, 2023). "Several studies have revealed that TAMs induce tumor chemoresistance through various mechanisms, and mammary tumors reduce the therapeutic response to anti-cancer drugs through mechanisms, such as IL-10/STAT3/Bcl2 signaling." (PMID 37369757, 2023). "TAMs-derived IL-6, IL-10, IL-22, and IL-23, together with T-lymphocyte-derived IL-9, IL-10, IL-37, and IL-35 and other cytokines, regulate the immune microenvironment of breast cancer tumors." (PMID 37542283, 2023). "The most frequently mentioned biomarkers for this cancer type came from the interleukin superfamily including IL-6, IL-8, IL-10, IL-2, IL-18, which is quite similar to what was found in breast cancer." (PMID 37181043, 2023).
breast cancer (continued). "Although their role in breast cancers is well-studied, much less is known about their relationship to specific subtypes of BC, and the link between ER status and IL-10 expression has yet to be fully investigated." (PMID 37894728, 2023). "In patients with breast cancer, elevated levels of IL-10 were observed in serum, which is closely related to tumor progression." (PMID 38102207, 2023). "Conversely, IL-10 (OR: 1.14, 95% CI: 1.03–1.26, P = 0.012) was associated with an increased risk of HER2-negative breast cancer." (PMID 37910571, 2023). "Another recent study in breast cancer indicated that the number of Tregs is closely correlated with that of (IL10+) Bregs in TIL aggregates in marginal regions of tumors." (PMID 37794508, 2023). "Genotyping of IL-10 SNP -1082 A/G was compared between 64 breast cancer cases with 64 healthy controls." (PMID 37501757, 2023). "Elevated serum levels of IL-10 have been found in breast cancer patients compared to healthy controls, and IL-10 serum levels correlated with cancer stage." (PMID 36945037, 2023). "The frequency of IL-10–producing Bregs correlated with shorter overall survival in bladder cancer patients and in breast cancer, and the coexistence of Bregs with regulatory T cells correlated with shorter metastasis-free survival in breast cancer." (PMID 36719372, 2023). "Our correlation analysis also indicated a negative correlation between disulfide dimethyl, a molecule with increased levels in breast cancer patients, and IL10, suggesting a potential link between this compound and anti-inflammatory processes." (PMID 38140285, 2023). "Higher serum IL-10 levels in breast cancer patients correlate with the clinical stages and metastatic cancer." (PMID 36693957, 2023). "Our study is the first to reveal the significance of IL-10 as a crucial factor in HER2-negative breast cancer." (PMID 37910571, 2023). "We mainly detected high expression of TGF-β, IL-1β, and IL-10 in basal-like breast cancer compared to healthy and luminal biopsies." (PMID 37340387, 2023). "Most existing studies on the effects of exercise on inflammatory factors and IGF systems in breast cancer survivors examine IL-6, IL-10, IL-1β, TNF-α, CRP, IGF-1, and IGFBP-3 levels." (PMID 36482346, 2022). "T cells in the mLN exhibited conversion from a pro-inflammatory state with high IFN-γ expression to an anti-inflammatory state with high expression of IL-4 and IL-10 in early- to late-stages of breast cancer development." (PMID 36232335, 2022). "Although the effects of IL-4 and IL-10 in breast cancer development are inconclusive toward anti- and pro-tumor effects, late-stage breast cancer patients exhibited high levels of these cytokines in their sera." (PMID 36232335, 2022). "IL-10 was the most dramatically upregulated cytokine, which has been proved to be related to the pathogenesis and progression of human breast cancer." (PMID 36038549, 2022). "Among anti-inflammatory cytokines, the same trend was noted: the content of IL-4 decreased (−15.1%), and IL-10 increased in breast cancer (+24.5%)." (PMID 36286034, 2022). "Accordingly, NRP2bHigh TAMs in murine mammary tumors had increased IL-10 levels compared to TAMs with low NRP2b." (PMID 35651620, 2022). "The effects of vitamin D3 on gene IL10 and IL10 plays an essential role in breast cancer have both been studied." (PMID 35150235, 2022). "It was shown that in the group of breast cancer patients, only the content of IL-2 and IL-10 changed statistically significantly, and in both cases, there was an increase in concentration." (PMID 36286034, 2022). "IL-10 also shares immunosuppressive function in addition to proven roles in antiangiogenic function in tumors and a correlation with improved prognosis in breast cancer." (PMID 35924165, 2022).